GPKOW (G-patch domain and KOW motifs)
Description:
RNA-binding protein involved in pre-mRNA splicing. As a component of the minor spliceosome, involved in the splicing of U12-type introns in pre-mRNAs (Probable).
Synonyms: GPATC5; GPATCH5; T54; Spp2; Mos2
Tractability: Small molecule: a structure with a bound ligand is known. PROTAC: UniProt records ubiquitination sites on it; ubiquitination databases record sites on it; its protein half-life has been measured.
Gene: Protein-coding gene on chromosome X (49,113,396 to 49,123,746, reverse strand). Ensembl gene ENSG00000068394.
Subcellular location: Nucleus
Subcellular location (Human Protein Atlas): Nucleoplasm
Pathways (Reactome):
Disease: Dengue Virus-Host Interactions
Metabolism of RNA: mRNA Splicing - Major Pathway
Gene Ontology:
Molecular function: protein binding; RNA binding; nucleic acid binding
Biological process: mRNA splicing, via spliceosome
Cellular component: nucleoplasm; nucleus; spliceosomal complex; U12-type catalytic step 2 spliceosome
Gene-disease validity (ClinGen):
ClinGen rates the evidence that GPKOW causes each of these diseases.
holoprosencephaly-hypokinesia-congenital contractures syndrome (X-linked): Moderate. An extremely rare and fatal central nervous system malformation occurring during embryogenesis, presenting prenatally with holoprosencephaly and fetal hypokinesia as major features.
Homologues: Orthologues: chimpanzee GPKOW (99% identical), macaque GPKOW (96% identical), pig GPKOW (83% identical), guinea pig GPKOW (79% identical), rat Gpkow (76% identical), mouse Gpkow (75% identical), rabbit GPKOW (71% identical), zebrafish gpkow (46% identical), tropical clawed frog gpkow (45% identical), Caenorhabditis elegans gkow-1 (25% identical), Drosophila melanogaster CG10324 (22% identical).
Diseases named in the same sentence as GPKOW in open-access papers:
GPKOW is named in the same sentence as 7 diseases in open-access papers, as found by Europe PMC text mining. Sharing a sentence is not in itself a finding about the gene and the disease. The quoted sentences say what the papers report.
behavioral disorders (1 paper, 2018). "Some candidates have been linked to intellectual disability (ID), such as CRBN, GPKOW, HERC1 and KCNA4, or to other behavioral disorders, such as CDC42EP4 and SLITRK5." (PMID 30102725, 2018).
cervical cancer (1 paper, 2022). A primary or metastatic malignant neoplasm involving the cervix. "Univariate Cox regression analysis screened 7 genes (FZR1, IMPDH1, HNRNPCL2, PCNA, GPKOW, XPA, and DDX39A) that were associated with the cervical cancer prognosis." (PMID 35909901, 2022). "Identification of KIN-related prognostic genes in cervical cancer revealed that a total of 5 genes (FZR1, IMPDH1, GPKOW, XPA, and DDX39A) were constructed for this risk score, and the results showed that CTLA4 expressions were negatively correlated with the risk score." (PMID 35909901, 2022).
GPKOW also shares sentences with these, for which no sentence is quoted: breast carcinoma (1 paper); infection (1); Intellectual disability (1); microcephaly (1); tumor (1).